SOCS3 (suppressor of cytokine signaling 3)
Diseases named in the same sentence as SOCS3 in open-access papers (continued):
Sharing a sentence is not in itself a finding about the gene and the disease.
infection (continued). "During experimental in vitro infection of permissive cell lines, VZV stimulates SOCS1 and, to a greater extent, SOCS3 in HaCaT human keratinocytes and MRC-5 human lung fibroblasts, and it also stimulates SOCS3 but not SOCS1 in THP-1 human monocytes." (PMID 31031749, 2019). "We report that infection of IC-21 mouse macrophages with MCMV propagated through the salivary glands of BALB/c mice, but not from tissue culture in C57BL/6 fibroblasts, transiently stimulates SOCS1 and SOCS3 mRNA transcripts, but not SOCS5 mRNA." (PMID 28182772, 2017). "The results showed that infection of HGEC cells with P. gingivalis, but not with heat-killed P. gingivalis, led to significant reductions in expression levels of mRNAs and proteins for SOCS-3, IRF-1, and EGFR, while LPS-Pg over time significantly increased the expression of these mRNAs and proteins." (PMID 28748038, 2017). "However, the relationship between SOCS3 and PCV2 that was observed in the in vitro infections may not mirror that in subclinical infections in vivo." (PMID 27581515, 2016). "However, the expression of Pkd2, Pkhd1, Kif12, Cadherin16 and Socs3, which are known as HNF-1β target genes, did not change (data not shown), and only a few genes, including NR1H4, MITF, SLC3A1, and SLCO4C1, were significantly upregulated 9 h after Ad-HNF1B infection." (PMID 27196561, 2016).
metabolic disorders (16 papers, 2010 to 2025). "Previous studies have shown that overexpression of SOCS3 is associated with impaired fatty acid oxidation and glucose metabolism, contributing to the progression of metabolic disorders." (PMID 39851554, 2025). "Previous studies have reported that SOCS3 is a target for treating metabolic disorders and influences insulin sensitivity and glucose homeostasis in the body." (PMID 37445769, 2023). "SOCS3 represents a promising target for the treatment of metabolic disorders." (PMID 41318472, 2025). "Over the past few years, SOCS3 has emerged as an interesting target to treat metabolic disorders." (PMID 35631263, 2022). "However, conditional knockout studies have shown that SOCS3 depletion can induce a number of inflammatory and metabolic disorders." (PMID 20526368, 2010). "However, mice born or raised by SOCS3 KO females presented a phenotype closer to that of undernutrition, rather than exhibiting evidence of metabolic programming that could lead to metabolic disorders in adulthood." (PMID 29536670, 2018). "SOCS3, an inhibitor of STAT3 which finally prevented inflammatory molecules transcription in many metabolic diseases, were found decreased after PPG injection and could be reversed by NaHS treatment." (PMID 33318871, 2021). "Mice lacking Socs3 die perinatally due to defective placental formation, whereas conditional Socs3 depletion induces inflammatory and metabolic disorders." (PMID 26788993, 2016).
bacterial infection (12 papers, 2012 to 2024). "Altogether, miR-30e qualifies to combat bacterial replication by enhancing innate immunity via targeting SOCS1 and SOCS3, two crucial negative regulators of innate immune signaling cascade during bacterial infections." (PMID 33585275, 2020). "In turbot, bacterial infection is also effective in increasing SOCS3 mRNA levels in various tissues including the liver and SOCS3 over-expression can inhibit TNFα and IL-1β expression in macrophages isolated from the head kidney." (PMID 32082258, 2020). "As SOCS1 and SOCS3 play essential roles in response to bacterial infections, they are therefore explicitly targeted for immune evasion." (PMID 29312162, 2017). "The most intended target is the interferon responses, mediated by STAT1 and controlled by SOCS1 and SOCS3, which play pivotal roles in the defense against bacterial infections." (PMID 29312162, 2017). "However, some studies have confirmed that miRNAs, such as miRNA-30e, can regulate the SOCS1 and SOCS3 genes during bacterial infection." (PMID 38668243, 2024). "Taken together, miR-30e targets SOCS1 and SOCS3 significantly which might regulate innate immunity during bacterial infection." (PMID 33585275, 2020). "Therefore, we sought to characterize miR-30e binding with SOCS1 and SOCS3 during bacterial infections." (PMID 33585275, 2020). "Furthermore, targeting STAT activity that is strictly regulated by SOCS1 and SOCS3 proteins, by inhibiting tyrosine kinases, could allow avoiding the subversion of the innate immune responses during a bacterial infection and therefore represents an attractive antibacterial therapeutic approach." (PMID 29312162, 2017). "SOCS1 and SOCS3 are target genes of STAT1 and STAT3, respectively, and are critical negative regulators of JAK-STAT signaling and thus maintain normal cytokine levels during viral or bacterial infections." (PMID 33968006, 2021). "Hence, we validated the expression of miR-30e, which is upregulated during bacterial infections/PAMPs and selected SOCS1 and SOCS3, important negative regulator of innate immune signaling pathways which are significantly targeted by miR-30e." (PMID 33585275, 2020). "Bacterial infection could be another case for IL-6 induction, because we found plaque of streptococcus in the inflamed skin area of some, but not all, Socs3 cKO mice (data not shown)." (PMID 22792286, 2012).
inflammation (11 papers, 2010 to 2025). Aberrant reaction of the microcirculation characterized by movement of fluid and leukocytes from the blood into extravascular tissues. "Myeloid Socs3 deficiency exacerbated CNV, reinforcing its protective role in retinal inflammation and NV." (PMID 40716081, 2025). "Bioengineered, cell‐penetrating recombinant SOCS3 comprises a new class of anti‐inflammatory intracellular therapy for acute liver inflammation and possibly inflammatory injury of other organs." (PMID 31378956, 2019). "Emerging data on activation and function of STAT3 and SOCS3 in the lung during acute inflammation suggest that these molecules may regulate pulmonary inflammation, and they have specifically been implicated in allergic airway inflammation." (PMID 20826374, 2010). "Indeed, the observation that flagellin does not promote wound healing, unlike alternative microbial products tested, may be a functional consequence of increased TLR5-driven TNF-α, with increased SOCS3, observed in chronic intestinal inflammation, exacerbating pathological TNF-α secretion." (PMID 25377316, 2015). "In order to investigate whether feeding a HFD for 16 weeks induces cardiac inflammation, protein expression of major pro-inflammatory cytokines was quantified as direct or indirect measure of TLR4 signaling (i.e., IL-6/TNF-α and SOCS-3, respectively)." (PMID 26539824, 2015). "Specifically, our results show that miR-19b suppresses its target SOCS3 to regulate MIP-3α production and mediate intestinal epithelial homeostatic function, and these alterations may influence mucosal repair following intestinal inflammation." (PMID 25997679, 2015).
lung (7 papers, 2015 to 2023). "Based on that, we exploredwhether the dysregulated expression of SOCS3 was associated with miR-650 in liver tumorcells." (PMID 34450627, 2021). "We plan to investigate whether the anti-inflammatory effect of MSCs can be enhanced after SOCS3 overexpression in this infectious lung injury model." (PMID 37175961, 2023). "The pSTAT3/SOCS3 axis is markedly altered during colorectal tumorigenesis and might be a target for IL-9-dependent regulation of epithelial cell proliferation." (PMID 35793807, 2022). "When GLP1 was administered (CD+GLP1+LT), it resulted in higher SOCS1 and SOCS3 expression than in the CD+LT group, and this was accompanied by less liver inflammation, evidenced by decreased levels of liver MPO, MDA, NO production, nitrotyrosine, and plasma vWF." (PMID 31835410, 2019).
cardiovascular diseases (6 papers, 2017 to 2025). "The inhibition of the main family members—SOCS1 and SOCS3—leads to sustained cytokine activation of STATs and contributes to the progression of inflammatory (including cardiovascular) diseases." (PMID 32824091, 2020). "Additionally, SOCS3 plays comparable roles in other cardiovascular diseases, reinforcing its potential as a universal biomarker across cardiovascular pathology." (PMID 40760666, 2025). "The consistent expression patterns of ANXA3 and SOCS3 in AMI and other cardiovascular diseases emphasize their universality and reliability." (PMID 40760666, 2025). "Other seed genes, such as FOS, SOCS3 and MCL1, should also be mentioned due to their special clinical value in cardiovascular diseases." (PMID 34271875, 2021). "Other seed genes, such as FOS, SOCS3 and MCL1, may also be potential targets for treatment due to their special clinical value in cardiovascular diseases." (PMID 34271875, 2021). "SOCS-based strategies to impair pathological JAK/STAT activity were already reported for the treatment of cardiovascular diseases confirming the anti-inflammatory and atheroprotective properties of the SOCS1/SOCS3 gene delivery in experimental atherosclerosis models." (PMID 32824091, 2020).
immune disorders (5 papers, 2017 to 2022). "Reduce type I IFN response through upregulating SOCS3 and leptin; cause other immune dysfunction associated with T cells and B cells." (PMID 34901094, 2021). "Recently, increasing evidences detailing suppressor of cytokine signaling 3 (SOCS3)’s broad-acting regulation in many biological processes implicated its role in immune disorders; thus, SOCS3 was identified as a key protein at the cross roads of numerous intracellular and pathological events." (PMID 29096659, 2017). "The elevated leptin and SOCS3 levels could reduce type I IFN response and cause other immune dysfunction associated with T cells and B cells in people with obesity." (PMID 34901094, 2021).
retinopathy (5 papers, 2013 to 2023). "It was recently reported that SOCS3 acts as an endogenous anti-angiogenic factor in endothelial cells during retinopathy of prematurity." (PMID 26260587, 2015). "Vascular SOCS3 deletion using Tie2-Cre resulted in increased pathological retinal angiogenesis in the murine models of oxygen-induced retinopathy, indicating that SOCS3 may be acting as an endogenous antiangiogenic under pathological conditions." (PMID 37569464, 2023). "In addition, a recent chemical screening study indicates that resveratrol is an inhibitor of SOCS3(suppressor of cytokine signalling 3) expression, depletion of which in vascular endothelial cells negatively impacts retinopathy." (PMID 24416337, 2014).
infectious disease (4 papers, 2017 to 2021). A disorder directly resulting from the presence and activity of a microbial, viral, or parasitic agent in humans. "More importantly the mechanism of leptin signaling in various infectious diseases is depends on SOCS3 expression as describes in NF-κB dependent pathway." (PMID 30534129, 2018). "Previous studies demonstrated that SOCS3-mediated IL-6/STAT3 signaling pathway regulates multiple cytokine signaling pathways in autoimmune and infectious diseases." (PMID 34147072, 2021).
neurological diseases (4 papers, 2012 to 2022). "SOCS3 may indeed be a therapeutic target in a number of neurologic diseases, however, strategies to selectively inhibit SOCS3 in neurons and oligodendrocytes, or induce SOCS3 in microglia and astrocytes, will need to be explored." (PMID 23226414, 2012).
hematological malignancies (3 papers, 2015 to 2020). "A large body of literature deals with the investigation of SOCS1 and SOCS3 in malignant diseases especially in the hematopoietic system demonstrating the importance of SOCS1 and SOCS3 in hematological disorders." (PMID 28753604, 2017).
liver (3 papers, 2019 to 2025). "Previous reports have demonstrated that FXR inhibits STAT3 phosphorylation by upregulating SOCS3 expression, thereby suppressing digestive system tumors." (PMID 39940889, 2025). "Additionally, studies have found that FXR inhibits the phosphorylation of STAT3 by upregulating the expression of SOCS3, thereby suppressing digestive system tumors." (PMID 39940889, 2025).
neurodegenerative disease (3 papers, 2022 to 2025). A disorder of the central nervous system characterized by gradual and progressive loss of neural tissue and neurologic function. "Previous literature has shown that dysfunction of SOCS3 might cause a variety of diseases, including immunological diseases, neurodegenerative diseases and tumors." (PMID 36690663, 2023).
adenocarcinoma (2 papers, 2010 to 2025). A common cancer characterized by the presence of malignant glandular cells. "In a G12D mutant mouse model of Kras-induced adenocarcinoma, we further show that increased glucose uptake by AMs is negatively correlated with SOCS3 secretion, and the inhibition of glycolysis restores their ability to secrete SOCS3." (PMID 41567211, 2025).
reproductive system neoplasm (1 paper, 2023). A benign or malignant, primary or metastatic neoplasm affecting the male and female reproductive system. "In addition, the expression of SOCS3 was significantly downregulated in PRAD and BRCA, which belong to reproductive system neoplasms, and COAD and LIHC, members of gastrointestinal cancer." (PMID 37025997, 2023).
vasculopathy (1 paper, 2021). "Moreover, our in vitro data suggest that inhibition of endothelial SOCS3 degradation is a promising avenue to prevent and/or revert vasculopathy during shock." (PMID 34138760, 2021).
SOCS3 also shares sentences with these, for which no sentence is quoted: overnutrition (5 papers); diabetic retinopathy (4); acute myocardial infarction (3); acute respiratory distress syndrome (3); Allergy (3); dilated cardiomyopathy (3); gestational diabetes (3); Graves’ orbitopathy (3); kidney cancer (3); Lymphadenopathy (3); malnutrition (3); age-related hearing impairment (2); Anxiety (2); benign tumors (2); chronic hepatitis (2); Chronic Lymphocytic Leukemia (2); chronic myelogenous leukemia (2); co-infection (2); conjunctivitis (2); diastolic heart failure (2); esophageal cancer (2); Herpes simplex infection (2); hypertrophic cardiomyopathy (2); idiopathic myelofibrosis (2); idiopathic pulmonary fibrosis (2); intracerebral hemorrhage (2); kidney disease (2); malignant fibrous histiocytoma (2); muscular dystrophy (2); Oral Squamous Cell Carcinoma (2).
A further 93 diseases each share a sentence with SOCS3 in 2 papers or fewer.